CAMK2A (calcium/calmodulin dependent protein kinase II alpha)
Diseases named in the same sentence as CAMK2A in open-access papers (continued):
Sharing a sentence is not in itself a finding about the gene and the disease.
asthma (1 paper, 2024). "CAMK2A encodes a protein belonging to the Calcium/calmodulin-dependent protein kinase II (CAMKII), and its oxidation promotes asthma through the activation of mast cells." (PMID 38291185, 2024).
cervical adenosquamous carcinoma (1 paper, 2022). An uncommon carcinoma arising from the cervix. "Notably, for histological type, CAMK2A, CYBB, IL1A, IL1B, and SLC25A5 were found to be upregulated in patients with cervical squamous cell carcinoma compared with those having cervical adenosquamous carcinoma (P < 0.05)." (PMID 36253777, 2022).
COVID-19 (1 paper, 2024). A disease caused by infection with severe acute respiratory syndrome coronavirus 2. "This suggests that the upregulation of CAMK2A may contribute to the cellular stress observed in SARS-CoV-2 infections, highlighting its potential role in the pathogenesis of COVID-19." (PMID 39459041, 2024).
experimental autoimmune encephalomyelitis (1 paper, 2023). An autoimmune demyelinating disease of the central nervous system that is produced experimentally in animals by the injection of homogenized brain or spinal cord in Freund's adjuvant. "Reduced levels of CAMK2A have been observed in experimental autoimmune encephalomyelitis (EAE), an animal model of multiple sclerosis." (PMID 37644477, 2023).
Headache (1 paper, 2023). Cephalgia, or pain sensed in various parts of the head, not confined to the area of distribution of any nerve. "For further verification, baseline CAMK2A levels were measured in a second, independent cohort of headache controls and MS patients (Mayo Cohort)." (PMID 37644477, 2023).
Hepatitis (1 paper, 2013). Inflammation of the liver. "We generated all of the Arch variants discussed in this paper within a similar construct containing the CaMKIIα (Camk2a) promoter and the woodchuck hepatitis post-transcriptional regulatory element (WPRE)." (PMID 23840563, 2013).
leukoencephalopathies (1 paper, 2022). "Consistent with the abundant metabolic protein signature of pons/medullary Camk2a neurons and the axonal predominance in this region, this regional proteomic signature was enriched in gene symbols related to inborn errorsof metabolism, leukoencephalopathies, and polyneuropathies." (PMID 35614064, 2022).
malaria (1 paper, 2025). Malaria is a serious and sometimes fatal disease caused by a parasite that commonly infects a certain type of mosquito which feeds on humans. "The upregulation of CAMK2A and ITPR1 in Ml during malaria reflects an active calcium-mediated immune response that promotes T cell activation, gene transcription, and inflammatory signaling to support effective host defense." (PMID 41333726, 2025).
medullary thyroid carcinoma (1 paper, 2021). "Although the mRNA expression of CaMKII’s endogenous inhibitor CAMK2N1 inversely correlates with the severity of medullary thyroid carcinoma, both CAMK2N1 (HR=2.1) and CAMK2A (HR=1.6) were overexpressed in the TCGA HNSCC patientswith worse outcomes." (PMID 34442426, 2021).
meningitis (1 paper, 2020). A disorder characterized by acute inflammation of the meninges of the brain and/or spinal cord. "We used Camk2a-CreERT2 mice to delete Bdnf from the cerebral cortex and hippocampus, and meningitis was induced by intracisternal infection with S. pneumoniae." (PMID 32676082, 2020).
migraine (1 paper, 2025). "Calcium/calmodulin-dependent protein kinase II alpha (CamKII) plays an important role in the nociceptive processing and the sensitization of central sensory neurons, which is essential in the development of the attacks; thus, CamKII might contribute to migraine pain." (PMID 40003563, 2025).
Moyamoya disease (1 paper, 2013). Moyamoya disease (MMD) is a rare intracranial arteriopathy involving progressive stenosis of the cerebral vasculature located at the base of the brain causing transient ischemic attacks or strokes. "We identified 165 significantly (p < 0.05) elevated autoantibodies in Moyamoya Disease, including those against CAMK2A, CD79A and EFNA3." (PMID 23518061, 2013).
muscle disorders (1 paper, 2021). "Increasing evidence that Camk2a is regulated by miRNA suggests miRNAs as potential therapeutic targets in muscle disorders." (PMID 33799993, 2021).
osteoporosis (1 paper, 2022). A condition of reduced bone mass, with decreased cortical thickness and a decrease in the number and size of the trabeculae of cancellous bone (but normal chemical composition), resulting in increased fracture incidence. "Then the RNA-seq verification by using total RNAs isolated from the femurs of normal and ovariectomized Wistar rats indicated that MFAP5, CAMK2A, and RGS4 in the ceRNA network were closely associated with osteoporosis." (PMID 35680981, 2022). "Besides, RNA-seq analysis verification of the target genes indicated that the expression of MFAP5, CAMK2A, and RGS4 was significantly changed in the OVX rats and is closely associated with osteoporosis." (PMID 35680981, 2022).
peripheral nerve injury (1 paper, 2020). Injury to a peripheral nerve. "RT-PCR verified Camk2a, an important gene of the Wnt signaling pathway, and demonstrated the importance of the Wnt signaling pathway in the repair of peripheral nerve injury, which is related to previous nerve injury." (PMID 32587647, 2020). "This indicates that Camk2a is a key gene for the treatment of peripheral nerve injury using massage." (PMID 32587647, 2020). "The RNA-Seq data in this study showed that Camk2a was upregulated after peripheral nerve injury and downregulated during the process of three-method and three-point intervention repair." (PMID 32587647, 2020).
Rett syndrome (1 paper, 2017). A severe neurodevelopmental disorder affecting the central nervous system.
tumor (30 papers, 2016 to 2025). "Such associations position CAMK2A as a regulator within the checkpoint network, potentially influencing tumor immune evasion." (PMID 41180485, 2025). "This association implies that CAMK2A may regulate signaling cascades governing immune cell recruitment or stromal cell proliferation, thereby shaping both tumor dynamics and host immune responses." (PMID 41180485, 2025). "Regarding the tumor pathological stage, it was observed that the expression of CAMK2A was significantly elevated in patients with stage III and IV BLCA compared to those in stages I and II (P < 0.001)." (PMID 40893939, 2025). "CAMK2A is recognized for its involvement in various cellular processes, including tumor initiation and progression." (PMID 40893939, 2025). "Immunohistochemical evaluation confirmed markedly increased CHMP4C and PYGB expression in LUSC compared with adjacent non-tumor tissues (P < 0.001), while CAMK2A expression was significantly enriched in normal tissues (P < 0.001)." (PMID 41180485, 2025). "CAMK2A displayed the opposite pattern, with higher expression in normal tissues and reduced levels in tumor tissues." (PMID 41180485, 2025). "The results indicated that SERPINI1 and CAMK2A were negatively correlated with tumor proliferation in LGG and GBM." (PMID 37706017, 2023). "In vivo, decreasing inoculation doses of 5 × 103 and 1 × 103 HCC827 CAMK2A-KD cells grown as monolayers, respectively, gave rise to significantly suppressed tumor growth rates." (PMID 32483123, 2020). "Consistent with this, reduced expression of Camk2a and Camk2b was validated in different EμMyc/Casp2−/− tumor samples." (PMID 30670683, 2019). "Increased expression of Wnt5a and Fzd1 and decreased expression of Lef1 and Camk2a were validated in different tumor samples by quantitative PCR." (PMID 30670683, 2019). "Levels of CaMK2A activated or phosphorylated states have a strong determining impact on tumor cell intracellular calcium levels." (PMID 28663722, 2017). "Since CaMK2A is also expressed in several other tumors, we anticipate a similar mechanism of action of Bacoside A to function in the eradication of various other tumor niches as well." (PMID 28663722, 2017). "Detailed investigation of the molecular mechanisms by which CAMK2A influences stromal and immune compartments may reveal novel therapeutic targets for modulating the tumor microenvironment." (PMID 41180485, 2025). "Moreover, the calcium/calmodulin‐dependent protein kinase, Camk2a and the metabotropic glutamate receptor, mGluR5, were upregulated in the hippocampus of mice that displayed spontaneous tumour regression." (PMID 40172096, 2025). "Furthermore, IHC for total CAMK2A proteins showed high-level expression in 40.8% of 377 AD, which featured more frequent and intense staining in tumor cell cytoplasm only." (PMID 32483123, 2020). "GBM high grade patient tissues showed strict regulation of phospho CaMK2A expression which would prevent cytoplasmic calcium burst that could otherwise adversely affect tumor cell survival." (PMID 28663722, 2017). "Notably, CAMK2A exhibited higher expression in normal lung tissues, whereas CHMP4C and PYGB were markedly overexpressed in LUSC, with their dysregulation associated with poorer clinical outcomes and a potential role in tumor progression and metastasis." (PMID 41180485, 2025). "Hence, these reports overall suggest that disturbances in the homeostatic levels of phospho CaMK2A (either by inhibition or via enhancement) may turn tumor cell vulnerable to death." (PMID 28663722, 2017). "A heatmap based on log2-fold change values demonstrated general overexpression of Wnt pathway genes in cancers, except for genes such as CAMK2A, SFRP1, and SOX17, which were underexpressed in several tumor types." (PMID 40002717, 2025). "In contrast, the proteins CAMK2A, IL33, IRF9, and TRAF5 were primarily expressed in normal tissues and exhibited reduced expression in tumor tissues." (PMID 40893939, 2025).
tumor (continued). "On the contrary, protein expressions of CAMK2A and TICAM2 were located primarily in normal tissues and weakly expressed in tumor tissues." (PMID 36253777, 2022). "Our analyses using the TIMER2.0 online tools showed that the mRNA expression level of CAMK2A had a positive relationship with the levels of dendritic cells (DCs), and had a negative correlation with levels of B cells and tumor purity levels (P < 0.05)." (PMID 36253777, 2022). "TCGA data in different types of GBMs showed CaMK2A expression, albeit lower than the normal tissues and other studies also supports this finding in GBM suggesting that tumor cells “need” but “keeps low levels” of this kinase in comparison to “normal controls”." (PMID 28663722, 2017). "The results were in high concordance with patient data as GBM tumor cell lines showed higher non-phospho CaMK2A levels vs. its phosphorylated form." (PMID 28663722, 2017). "These predicted three DFT1-specific in-frame fusion genes, PDZD11-RFX2, CAMK2A-NEURL1B, and EZH2-ETNK2; the latter two potential fusion genes were found in only one of two analyzed DFT1 tumors, and are thus unlikely to have arisen early in DFT1 tumor evolution." (PMID 29634948, 2018).
cancer (28 papers, 2008 to 2026). A tumor composed of atypical neoplastic, often pleomorphic cells that invade other tissues. "CAMK2A displayed broad positive correlations, with distinct clusters of strong associations in several cancers, whereas CHMP4C and PYGB exhibited heterogeneous profiles characterized by both positive and negative associations." (PMID 41180485, 2025). "Not only is CAMK2A implicated in cognitive functions, neurodevelopment, and certain cancer types, but a study parallel to ours also unveiled its potential to augment synaptic plasticity in MCAO mice." (PMID 38188159, 2024). "CAMK2A exhibited strong positive correlations across multiple cancer types, with distinct clusters indicating significant associations in specific cancers." (PMID 40893939, 2025). "A few reports have suggested CAMK2A plays a role in cancers of the breast, colon, and stomach, but involvement in lung or in TIC maintenance has not been reported." (PMID 32483123, 2020). "Taken together, the data suggested CAMK2A mediated in vitro cancer phenotypes and drug resistance through reducing EZH2 and release of SOX2 from epigenetic repression." (PMID 32483123, 2020). "Further, cancer cells with induced drug resistance showed increased levels of activated CAMK2A, and co-treatment with its pharmacological inhibitor restored relative sensitivity." (PMID 32483123, 2020). "Epithelial–mesenchymal transition (EMT), one of the cancer hallmarks, is also controlled by Ca2+ levels through CAMK2A." (PMID 32629766, 2020). "CAMK2A, a gene related to NF-kB-activation and has been demonstrated to act anti-apoptotic in cancer stem-like cells, is the third-most up-regulated gene at DUX4-REL41." (PMID 30862934, 2019). "While manipulation of CAMK2A expression in cancer cells induced corresponding functional changes consistent with its TIC supportive role including self-renewal, xenograft tumorigenecity at low cell doses, and resistance to targeted or cytotoxic therapy, silencing SOX2 abrogated these effects." (PMID 32483123, 2020). "Further studies in larger series of patients are warranted to elucidate this question and determine the specific role of those cancer associated genes (INPP5A, CDX1, MB, CAMK2A, APOL6 vs. VPS53, FAM57A, GEMIN4, SFRS13, ELP2P, GLOD4, CSF2RA and IL3RA), differentially altered in both groups of tumors." (PMID 21811587, 2011). "To verify the role of SERPINI1 and CAMK2A, we first evaluated the expression of SERPINI1 and CAMK2A in TCGA‐LGG (Grade2 & Grade3), GBM and para‐cancer." (PMID 37706017, 2023). "The cancer-upregulated exRNAs that were also most frequently detected among the cancer samples that came from RAC2, KRAS, and CAMK2A." (PMID 31481608, 2019). "Additionally, CAMK2A, the third most up-regulated gene at DUX4 relapse, acts as an anti-apoptosis regulator by activating NF-kB in metabolic stress-resistant cancer stem cells." (PMID 30862934, 2019).
infection (18 papers, 2013 to 2025). The state of being infected such as from the introduction of a foreign agent such as serum, vaccine, antigenic substance or organism. "Infection of the shGrin2b virus into the dorsal hippocampus of Camk2a-Cre mice resulted in a significant reduction in GluN2B expression, without affecting GluN1, GluN2A, or PSD-95 levels in the synaptosomal fraction." (PMID 40338662, 2025). "Given the functional similarities between CAMK2A and CAMK2B, the presence of CAMK2B in this study points to its potential involvement in rabies pathogenesis, particularly during the early phases of infection when neuronal communication is first disrupted." (PMID 41441337, 2025). "Infection of the dorsal hippocampus with shGrin2b did not significantly affect MWM performance in adult Camk2a-Cre mice." (PMID 40338662, 2025). "A recent study involving proteomics of human tissue showed the effect of inflammation post-infection on the basal ganglia and the brain stem and suggested changes in trafficking in AMPA receptors via inflammation, along with increased abundance of protein kinases PRKCG, PRKCB, and CAMK2A/B." (PMID 38002279, 2023).
neurodevelopmental disorder (8 papers, 2020 to 2025). A behavioral and cognitive disorder with onset during the developmental period that involves impaired or aberrant development of intellectual, motor, or social functions. "These lines of clinical data strongly suggest the possibility that CAMK2A P212L mutation could alter the biochemical properties of CaMKIIα that underlie neurodevelopmental disorders." (PMID 36117912, 2022). "In addition, in the paralogous isoform CAMK2B, P213L mutation, which is in the same position as P212L in CAMK2A, has been found in a patient with neurodevelopmental disorders." (PMID 36117912, 2022).
neurological disorders (6 papers, 2009 to 2023). "Though many mutations in CAMK2A were linked to a variety of neurological disorders, the multiplicity of its functional substrates renders the systematic molecular phenotyping challenging." (PMID 36117912, 2022). "Our discovery of a novel neuro-developmental syndrome caused by biallelic CAMK2A mutations further broadens the spectrum of human neurological disorders caused by the CAMK2 family of kinases." (PMID 29784083, 2018). "Next, we contrast Camk2a-neuron and Aldh1l1-astrocyte proteomes and identify brain region-specific proteomic differences within both cell types, some of which might potentially underlie the selective vulnerability to neurological diseases." (PMID 35614064, 2022). "We thus expect that single-nucleotide polymorphisms or other mutations that modulate CAMK2B, and potentially CAMK2A, alternative splicing alter CAMK2 functionality and may be involved in a variety of neurological diseases." (PMID 36543542, 2023). "Together, our data demonstrate that a recessive germline mutation in CAMK2A leads to neurodevelopmental defects in humans and suggest that dysfunctional CAMK2 paralogs may contribute to other neurological disorders." (PMID 29784083, 2018).
psychiatric disorder (4 papers, 2018 to 2022). A disorder characterized by behavioral and/or psychological abnormalities, often accompanied by physical symptoms. "Deficiency in CAMK2A protein has been linked to psychiatric disorders indicating its importance in the observed phenotype." (PMID 29743870, 2018).
lung (1 paper, 2020). "Multiple lung AD cell lines with various CAMK2A expression levels were manipulated to model their in vitro and in vivo roles on TIC phenotypes." (PMID 32483123, 2020).
CAMK2A also shares sentences with these, for which no sentence is quoted: ischemia (5 papers); memory impairment (5); ischemic stroke (4); neuroblastoma (4); osteosarcoma (4); Cerebral ischemia (3); neurodegenerative disease (3); Pain (3); alcohol dependence (2); brain diseases (2); chronic kidney disease (2); cognitive decline (2); colorectal cancer (2); esophageal squamous cell carcinoma (2); fragile X syndrome (2); glaucoma (2); hippocampal atrophy (2); Hypertension (2); injury (2); mood disorder (2); neuropathic pain (2); oligodendroglioma (2); Seizure (2); temporal lobe epilepsy (2); α-thalassemia (2); alcohol (1); alcohol withdrawal syndrome (1); amyotrophic lateral sclerosis (1); Apathy (1); astrocytoma (1).
A further 60 diseases each share a sentence with CAMK2A in 1 paper.